CD47 (CD47 molecule)
Diseases named in the same sentence as CD47 in open-access papers (continued):
Sharing a sentence is not in itself a finding about the gene and the disease.
cancer (continued). "Furthermore, on TKI-sensitive cell lines, EGFR inhibition significantly reduced CD47 expression on the surface of preapoptotic cells, favoring more efficient engulfment of cancer cells by monocyte-derived dendritic cells." (PMID 33015199, 2020). "CD47 blocking agents, such as monoclonal antibodies targeting CD47/SIRPα, could interrupt the interaction between cancer cells and macrophages and induce phagocytosis, potentially providing an effective method of cancer therapy." (PMID 33469516, 2020). "Likewise, strategies to block CD47 and PD-L1 expressions on cancer cells are of immense interest as they enhance the antitumor response." (PMID 32377203, 2020). "Of note, CD47 does not seem to be directly involved in regulating the proliferation and viability of cancer cells, as CD47-deficient cancer cells are phenotypically indistinguishable from their parental CD47 expressing cells in cell culture." (PMID 33015199, 2020). "The advantages using cancer-CMC-NPs are immune-evading properties (CD47), homotypic targeting behavior (cadherin, integrins), and cancer immunotherapy (vaccination) with improved tumor-specific accumulation, enhanced circulation, and enhanced drug or gene delivery avoiding side effects." (PMID 32937963, 2020). "Engineered exosomes that antagonize the interaction between CD47 and SIRPα promote intensive T cell infiltration in syngeneic mouse models of cancer, indicating that exosome-mediated immunotherapy targeting the CD47/SIRPα axis is one of the most promising new strategies for immuno-oncology." (PMID 33168028, 2020). "The CD47-SIRPα axis is at the spotlight of cancer immunotherapy research." (PMID 33015199, 2020). "CD47 is an immunoglobulin that is overexpressed on the surface of many types of cancer cells." (PMID 32082311, 2020). "Therefore, CD47-signaling on dendritic cells is crucial for effective immune response in inflammatory conditions such as cancers and infections." (PMID 32882841, 2020). "In this way, cancer cells exploit the “don't eat me signal” provided by CD47." (PMID 33015199, 2020). "In addition, anti-CD47 mAbs decrease the ability of Treg cells to overcome immune evasion by cancer cells and increase the capacity of CD8+ T cells to exhibit an effective antitumor cytotoxic function." (PMID 32370748, 2020). "Therefore, blocking CD47 is a promising therapeutic approach to augment the neutrophil-mediated killing of cancer cells." (PMID 33105656, 2020). "The anti-CD47 antibody is currently under clinical trial for the treatment of cancer and could also have amenable therapeutic potential against infectious diseases." (PMID 32882841, 2020). "Cancer cells were more invasive and exhibited higher CD47 expression." (PMID 32231135, 2020). "CD47 is expressed widely on both cancer and normal cells throughout the body." (PMID 32281289, 2020). "However, there are limited number of studies on targeting CD47 in MM, while prior results from other types of cancers suggest encouraging outlook for similar strategies in treating MM." (PMID 32012878, 2020). "However, the CD47-mediated regulation of phagocytotic removal of different types of cancer cells remains incompletely understood." (PMID 32082311, 2020). "Strategies for targeting CD47 are becoming a hot spot for cancer therapy." (PMID 33469516, 2020). "Knockdown of ENO1 blocked CD47-mediated cancer cell proliferation and metastasis." (PMID 32226539, 2020). "Moreover, it was demonstrated that treatment with anti-human CD47 of cancer stem cells isolated from the Triple-Negative MDA-MB-231 cell line decreases proliferation and up-regulates tumour suppressor genes." (PMID 33574894, 2020). "Examples of the impact of anti-CD47 treatments in different types of cancer." (PMID 32082311, 2020). "Here, a novel oncolytic adenovirus carrying a signal regulatory protein‐α (SIRPα)‐IgG1 Fc fusion gene (termed SG635‐SF) was constructed, which could block the CD47 ‘don't eat me’ signal of cancer cells." (PMID 31899582, 2020).
cancer (continued). "The proteolysis-resistant analog pep-20-D12 could serve as a potential candidate for cancer immunotherapy by blocking CD47/SIRPα, especially in combination with RT to elicit synergistic effects." (PMID 33020240, 2020). "In addition to the anti-phagocytic effect of cancer cells by macrophages, “don’t eat me” signaling CD47 gene expression also significantly increased in Colon-26MGS." (PMID 32325684, 2020). "Antibodies blocking the interaction between CD47 and its receptor on macrophages, signal regulatory protein alpha (SIRPα), have been shown to diminish the inhibitory signaling transduced to macrophages via the CD47-SIRPα axis, thus enabling the phagocytosis of cancer cells." (PMID 33603751, 2020). "We measured expression levels of CD47 in 22 paired carcinoma-normal endometrial tissues." (PMID 32984001, 2020). "We found that CD47 expression was upregulated in carcinoma tissues." (PMID 32984001, 2020). "Also demonstrated to be ectopically expressed in several other cancer types, strong evidence abounds implicating CD47 in the pathogenesis and progression of malignancies by its inherent ability to inhibit the phagocytosis of transformed or malignant cells." (PMID 31861233, 2019). "Siglec-10 binds to CD24, a ligand that, like CD47, is overexpressed in multiple human cancers." (PMID 31801627, 2019). "However, in the course of cancer development, some cancer cells also express another protein, CD47, a kind of “don’t eat me” signal." (PMID 31528120, 2019). "The interaction CD47-SIRPα has been intensively investigated as potential cancer therapy." (PMID 31921125, 2019). "Thus, cancer cells not only express CD47 but also pro-phagocytic signals, however, normal cells express CD47 but lack pro-phagocytic signals." (PMID 32038992, 2019). "CD47 is an immune-regulatory molecule expressed on the surface of many cells and all human cancers." (PMID 30941125, 2019). "To design a system to test the hypotheses, we chose one of the most studied immune checkpoint mechanisms in cancer - the CD47-SIRPα interaction." (PMID 31882679, 2019). "Cancer cells upregulate CD47 to evade macrophage clearance by inhibiting phagocytosis." (PMID 30770827, 2019). "CD47, also known as integrin-associated protein (IAP), is a transmembrane protein, which attenuates the prophagocytosis (‘do not eat me’ signal) function of CRT, the expression of which is increased when high levels of CRT are present on cancer cell surfaces." (PMID 30813267, 2019). "Anti-CD47-targeted therapy may represent a promising strategy to treat cancer and to improve long-term survival." (PMID 30653520, 2019). "Furthermore, a majority of cancer cells express a high amount of CD47 at their surface, which interacts with signal regulatory protein alpha SIRPα on myeloid cells such as macrophages to transmit the “do not eat me” signal." (PMID 31547627, 2019). "Targeting CD47 for cancer therapy has sparked great interest." (PMID 31540045, 2019). "In summary, these data indicate that ATCs express the dominant pro-phagocytic molecule calreticulin, as well as the “don't eat me” signal CD47 and the immune checkpoint molecules PD-1 and PD-L1, all of which are currently targeted therapeutically in other types of cancer." (PMID 30938231, 2019). "Preclinical studies demonstrated that activation of macrophages through blockage of the CD47/SIRPɑ axis may effectively treat various cancers." (PMID 31183992, 2019). "Functional relevance of CD47 overexpression is indicated by our data; although gefitinib down-regulates CD47 and increases ecto-CRT in almost all cell lines tested, it is the decrement of CD47 that results in enhanced phagocytosis of cancer cells by dendritic cells." (PMID 32082304, 2019). "Consequently, several CD47 targeting agents have entered the clinic for a number of cancer indications spanning both hematologic malignancies and solid tumors." (PMID 32038992, 2019).
cancer (continued). "In order to determine the expression levels of CD47 among UM samples at different cancer stages, and to determine the potential mechanisms involved in the regulation of its expression, we interrogated the TCGA (The Cancer Genome Atlas) dataset." (PMID 31277366, 2019). "By expressing CD47, cancer cells will block “eat me” signals (such as the molecule calreticulin, which marks the cells for phagocytosis) by engaging the signal regulatory protein alpha (SIRP1α) on the surface of macrophages and limiting their cellular rearrangement for efficient engulfment." (PMID 30832375, 2019). "It is reported that CD47 was highly expressed in many cancer cells or tissues, and binded to phagocytes to inhibit normal phagocytosis, suggesting that CD47 expression may affect the distribution and expression of macrophages." (PMID 31528120, 2019). "Second, CD47 and calreticulin cell surface protein levels on cancer cells were highly correlated." (PMID 32038992, 2019). "Furthermore, the expression of CD47 on cancer stem cells (CSCs) suggests a role in cancer recurrence." (PMID 31277366, 2019). "Thus, CD47 is a prominent new target in cancer immunotherapy, particularly in B-cell malignancies, in which e.g. combination of a CD47 antibody with the CD20 antibody rituximab is being explored in clinical trials." (PMID 30710089, 2019). "Interactions between SIRPα on phagocytic cells and CD47 on phagocytosed targets, such as erythrocytes, cancer cells, and apoptotic cells, act as a ‘don’t eat me’ signal and thereby control erythrocyte homeostasis, elimination of cancer cells, and the formation of arteriosclerotic plaques." (PMID 30910011, 2019). "The important corollary of these findings is that cancer cell expression of SLAMF7 does not associate with or predict for therapeutic effects of CD47-targeting drugs." (PMID 30710089, 2019). "CD47 molecule, a ubiquitous cell-surface receptor that promotes immune evasion by interacting with signal-regulatory protein alpha (SIRPα), is a member of immunoglobulin (Ig) superfamily and is considered as a promising cancer biomarker." (PMID 31461846, 2019). "Indeed, almost every type of cancer cell expresses CD47 at their cell surface, which is a molecule known for its role on normal, healthy cells as a “don’t eat me” signal to phagocytosing macrophages." (PMID 30832375, 2019). "In addition, miRNAs have been described as regulators of stem cells and related with the overexpression of CD47 in cancers." (PMID 31921125, 2019). "Since the balance between CD47 and ecto-CRT expression determines the susceptibility of cancer cells to engulfment by phagocytes, based on our results, we hypothesized that gefitinib treatment could promote phagocytosis of NSCLC cells by CD47 down-regulation." (PMID 32082304, 2019). "Similarly, we observed that the expression of GCLC, NLRP3 and CD47 are downregulated in both groups of non-cancer cells treated with either LIUS or mild hyperthermia." (PMID 31355136, 2019). "The data previously generated, along with the information from the present study, strongly support the development of anti-CD47-based therapy for UM patients, as it may represent a promising strategy to treat cancer and to increase survival." (PMID 31277366, 2019). "CD47 is a widely expressed cell surface protein that functions as an immune checkpoint in cancer." (PMID 30133535, 2018). "Moreover, IFNγ was significantly upregulated when mice treated with anti-CD47, suggesting that while TAMs are engulfing cancer cells, the antigen presenting function of the macrophages induces CD8+ T cells to further eradicate cancer cells." (PMID 30062558, 2018). "Therapeutic blockade of the CD47 pathway may stimulate antitumor immunity and improve cancer therapy." (PMID 30133535, 2018). "The CD47-SIRPα axis is now recognized as an important innate immune checkpoint in cancer." (PMID 30133535, 2018).
cancer (continued). "Thus, the CD47–SIRPα axis has become an attractive target for developing novel cancer immunotherapies, and anti-CD47 blockades are currently investigated by several clinical trials in various solid tumors." (PMID 30061885, 2018). "Therefore, to enhance the ability of the immune system against various cancers, CD47 can be used as a novel target for cancer immunotherapy." (PMID 29329591, 2018). "Cancer cells upregulate CD47 expression in order to evade antitumor immunity." (PMID 31544856, 2018). "This new knowledge that CRT binds to asialoglycoproteins, which are often hidden by sialic acid, is the first step in dissecting the mechanism of PrCR initiation, which can be targeted in disease states such as cancer alone, or in combination with CD47 inhibition." (PMID 30097573, 2018). "CD47 serves as an anti-phagocytic receptor that is upregulated by cancer to promote immune escape." (PMID 31544856, 2018). "As such, a rationale for therapeutically targeting CD47 in cancer has evolved." (PMID 31544856, 2018). "However, its role in viral immunity is poorly understood but will be important for evaluating experimental cancer therapeutics targeting CD47." (PMID 30643501, 2018). "However in cancer cells, the increased expression of CD47 can enable pro-cancerous immunosuppression by deregulating the phagocytic uptake of cancer cells by the innate immune cells." (PMID 29707136, 2018). "Thus, humanized CD47-CAR-T cells effectively and specifically killed cancer cell lines and produced cytokines in a CD47-dependent manner." (PMID 29065481, 2017). "In Jurkat cancer cells we also observed a great CD47 reduction (60%) 48 h after JQ1 treatment." (PMID 28378740, 2017). "In summary, CD47 is regulated by sets of different enhancers and SEs in different cancer types." (PMID 28378740, 2017). "CD47 blockade is considered as another immune checkpoint therapy for cancer." (PMID 28484448, 2017). "This suggests that cancer cells with CD47 SEs have newly acquired these SEs, which perhaps increase the probability of high CD47 expression by simultaneously recruiting multiple constituent enhancers, including the constituent enhancers that have specific regulatory activity." (PMID 28378740, 2017). "The expression of CD47 is frequently increased in human cancer cells." (PMID 29050218, 2017). "While these cells may show different responses to chemotherapies, cancer cells and the TICs both express high levels of the ‘don't eat me’ signal CD47 to prevent the macrophages from engulfing and eliminating them." (PMID 28380460, 2017). "Our goal is to identify alternative mechanisms and pathways directly upstream of CD47 that might be targeted to downregulate CD47 expression, thereby making cancer cells vulnerable to phagocytosis and immune clearance." (PMID 28378740, 2017). "Although the mechanism responsible for this remains largely unknown, blockade of the interaction between CD47 and SIRPα is emerging as a promising immunotherapeutic approach in the treatment of cancer." (PMID 29050218, 2017). "In addition, our analyses of H3K27ac ChIP-Seq data indicated that CD47 is regulated by different sets of enhancers or SEs in different cancer cell types." (PMID 28378740, 2017). "Thus, CD47 and humanized CD47-CAR-T cells can be used as a novel immunotherapy approach to eliminate CD47-positive cancers." (PMID 29065481, 2017). "The use of CD47-CAR-T cells provides a novel type of anti-cancer cellular therapeutics." (PMID 29065481, 2017). "Thus, CD-47-CAR-T cells kill and secrete IL-2 cytokine in a CD47-dependent manner based on CD47 expression on the surface of cancer cells that is consistent with cytotoxicity data." (PMID 29065481, 2017). "Future studies will be needed to optimize CD47-CAR-T cell therapy for different types of cancer." (PMID 29065481, 2017). "However, the anti-cancer activity observed with anti-CD47 mAbs is Fc effector dependent as are the side effects observed on RBC indices." (PMID 28234345, 2017).
cancer (continued). "Thus, CD47-CAR-T cells can be used as a novel cellular therapeutic agent for treating different types of cancer." (PMID 29065481, 2017). "Although targeting CD47 represents a unique mechanism of action and may have broad applicability across various cancers, the ubiquitous nature of CD47 presents a therapeutic challenge." (PMID 28234345, 2017). "CD47, also called integrin-associated protein (IAP), is a tumor-associated antigen (TAA) expressed on normal, healthy hematopoietic stem cells (HSC) and overexpressed on the surface of a variety of cancer cells." (PMID 29312320, 2017). "Thus, this is the first report demonstrating a novel approach to target cancer cells with CD47-CAR-T cells." (PMID 29065481, 2017). "Importantly, blockade of CD47:SIRP-α interactions stimulated enhanced antitumor responses in several mouse models of human cancer, and trials of anti-CD47 antagonistic monoclonal antibodies are underway in humans." (PMID 28515726, 2017). "Due to the critical role CD47 has in protecting cancer cells from phagocytosis, we hypothesized that SEs could be evolved by cancer or pre-cancer cells to induce overexpression of CD47, thus providing the cells with a selective advantage for growth and spread." (PMID 28378740, 2017). "In addition to facilitating cancer cell immune evasion, CD47 also affects T cell and NK cell homeostasis." (PMID 28515726, 2017). "This information altogether suggests that combining treatments, for instance the infliximab antibody with the CD47 antibody, could be considered as a therapy to increase engulfment of cancer cells by macrophages." (PMID 28378740, 2017). "Anti-CD47 antibodies have been shown to inhibit the progression of several types of cancer." (PMID 28380460, 2017). "Whether ERK activation similarly plays a role in regulation of CD47 in other types of cancers remains to be investigated." (PMID 29050218, 2017). "Furthermore, CD47 mRNA expression levels are correlated with a decreased probability of survival for multiple types of cancer." (PMID 28886030, 2017). "A potential application of the finding that low levels of 4N1K can enhance anti-CD47-induced phagocytosis is that this might be used to enhance anti-CD47 cancer therapy in vivo." (PMID 28977832, 2017). "We then examined whether ZF1 could functionally block the interaction between CD47 and SIRPα, which were known to inhibit macrophage-mediated phagocytosis of CD47+ cancer cells." (PMID 27863402, 2016). "Besides, anti-CD47 blocking antibodies represent one of the most successful way to achieve desirable anti-cancer therapeutic effects." (PMID 27863402, 2016). "Multiple strategies had been developed for cancer therapy by targeting CD47/SIRPα interaction." (PMID 27863402, 2016). "Cancer cells could escape phagocytosis via CD47 overexpression, which in turn signaling to macrophage via binding SIRPα on cell surface." (PMID 27863402, 2016). "Therefore, elevated CD47 expression correlates with known markers and regulators of stem cell maintenance in breast and other cancers." (PMID 26840086, 2016). "Several strategies have been used to target CD47 in cancer therapy." (PMID 27839516, 2016). "CD47 overexpression has been reported in many human cancers; however, its expression in NSCLC remains unclear." (PMID 27411490, 2016). "Antibodies or other blocking agents targeting CD47/SIRPα could block communication between cancer cells and macrophages and induce phagocytosis, potentially an effective method of cancer therapy." (PMID 27863402, 2016). "CD molecules are promising targets for novel cancer immunotherapies such as CD47." (PMID 25971253, 2015). "Their results show that CD47 is detected at an elevated level on nearly all these cancer cells." (PMID 26674012, 2015). "Thus, CD47-conjugated gold nanoshells exhibited considerably strong antitumor effects that not only damaged the cancer cells through direct photoablation but also triggered the host antitumor immunity." (PMID 26318039, 2015).